ATRX (ATRX chromatin remodeler)
Diseases named in the same sentence as ATRX in open-access papers (continued):
Sharing a sentence is not in itself a finding about the gene and the disease.
glioma (continued). "In primary gliomas, DNA methylation downregulates ATRX, inhibiting DNA damage repair through the ATRX/EZH2 complex-PARP1 axis and increasing sensitivity to TMZ." (PMID 39479502, 2024). "Another study that developed murine glioma models based on ATRX KO followed by mutant IDH1 overexpression described upregulated pro-inflammatory gene programs and Nfkb1 signaling as characterized by single cell RNAseq and ATAC-seq23." (PMID 38272925, 2024). "Compared to parental cells, TMZ-resistant glioma cells expressed higher levels of ATRX and were enriched in EZH2." (PMID 39479502, 2024). "Specifically, based on their results assessing IDH mutations associated with ATRX and H3K27me3, immunostainings can help to determine the necessity of 1p/19q codeletion testing in IDH-mutant gliomas." (PMID 39456545, 2024). "SIRT2, which was identified through multiomics synthesis as a potential driver gene in ATRX-null gliomas, is overexpressed." (PMID 39479502, 2024). "Loss of ATRX expression, often coupled with IDH1 mutations, is common in gliomas and is associated with specific subtypes such as astrocytomas." (PMID 39459454, 2024). "Based on the results presented, the ATRX and IDH mutations conferred a survival advantage for glioma patients." (PMID 38633919, 2024). "Conversely, in TMZ-resistant glioma cells, DNA demethylation enhances ATRX expression, promoting DNA damage repair to counteract drug effects like TMZ." (PMID 39479502, 2024). "The 2016 WHO central nervous system tumor classification further stratified gliomas by incorporating genome‐based criteria, including IDH and ATRX mutations and 1p/19q codeletions." (PMID 37545464, 2024). "Based on their molecular profile, a significant proportion of adult-type gliomas can be subtyped by IDH (IDH1 or IDH2) and ATRX mutation status, as well as 1p19q codeletion." (PMID 38106649, 2023). "In the study presented here, we analyzed the genetic patterns of ATRX-deficient IDH-wildtype and H3-wildtype adult high-grade gliomas in comparison with ATRX-intact GBs using CGP." (PMID 37891325, 2023). "In the TCGA-glioma dataset, risk Scores were significantly correlated with age, Grade, survival status, IDH status, MGMT status, ATRX status and BCR status." (PMID 36778644, 2023). "Of note, TERT mutations and ATRX mutations are mutually exclusive in gliomas, and the exact mechanism of how ATRX mutations, in particular, induce ALT in gliomas is still under investigation." (PMID 37626776, 2023). "Disruption of ATRX expression in humans leads to the development of α-thalassemia and cancer, especially glioma." (PMID 38003676, 2023). "When prospectively tested on 153 patients, the model predicted WHO glioma classification with a mean 93.3% accuracy, including IDH mutation (94.7%), 1p19q co-deletion (94.1%), and ATRX mutation (91.0%)." (PMID 38161802, 2023). "ATRX-deficient IDH-wildtype and H3-wildtype adult high-grade gliomas occur in small numbers even in large publicly available databases." (PMID 37891325, 2023).
glioma (continued). "ATRX/DAXX mutations associated with ALT telomere maintenance are most frequently observed in liposarcomas, adult gliomas, pancreatic neuro-endocrine tumors, and osteosarcomas." (PMID 37107548, 2023). "A recent study describes that loss of ATRX, another epigenetic modulator in both adult and pediatric glioma, epigenetically induces the expression of PD-L1 and several immunosuppressive cytokines, eliciting tolerogenic mechanisms in ATRX-mutant glioma." (PMID 36647827, 2023). "Standard glioma biomarker data collected into BRAIN includes 1p19q codeletion, IDH mutation, MGMT methylation, ATRX mutation and TERT promotor mutation with a free text field to capture other biomarkers of interest." (PMID 35655179, 2022). "The ATRX KO malignant glioma cell lines incorporated EdU similar to the ATRX WT cell lines, indicating that ATRX KO cells replicate and proliferate at normal rates, which is important to assess the toxicity caused by the drug treatments." (PMID 35406561, 2022). "Next, we studied three of these drugs (ibrutinib, niclosamide, and pazopanib) in isogenic ATRX KO high-grade glioma cell lines previously generated by CRISPR/Cas9." (PMID 35406561, 2022). "Three different ATRX KO high-grade glioma cell lines showed sensitivity to pazopanib and three additional RTKi (sorafenib, nintedanib, and sunitinib), all of which target PDGFR and other RTKs." (PMID 35406561, 2022). "We used CRISPR/Cas9 engineered ATRX KO high-grade glioma cell lines and empty vector (EV) control cell lines that were generated in a previous study." (PMID 35406561, 2022). "While our multivariable models adjust for tumour subtype, we investigated age-associations of ATRX and IDH1 SNV mutation frequency in lower grade gliomas in greater detail." (PMID 35017538, 2022). "The three isogenic (EV and ATRX KO) glioma cell lines were treated with different concentrations (0.3 μM and 0.6 μM) of CP-673451 for 48 h to assess cell viability." (PMID 35406561, 2022). "Conversely, 1p/19q codeletion status should be determined in all IDH-mutant gliomas with retained nuclear expression of ATRX." (PMID 36249063, 2022). "We found that all the ATRX KO high-grade glioma cell lines are more sensitive to CP-673451 at 0.6 μM compared to their WT counterparts." (PMID 35406561, 2022). "TERTp mutations activate TERT to maintain telomeres in cancer cells, but generally at a shorter length relative to other telomere maintenance mechanisms, such as alternative lengthening of telomeres in ATRX mutant glioma." (PMID 36130485, 2022). "Given that high-grade gliomas frequently harbor mutations in the SNF2 family chromatin remodeler ATRX, we performed a screen to identify FDA-approved drugs that are toxic to ATRX-deficient cells." (PMID 35406561, 2022). "This was consistent with the findings suggesting that ATRX knockout can suppress DNA damage repair by regulating ATM pathway or mediating PARP1 instability to sensitize glioma cells to TMZ treatment." (PMID 35720326, 2022). "In gliomas, TERT expression and TERT promoter mutation are considered to reliably indicate telomerase activation, while ATRX mutation and/or loss indicates an alternative lengthening of telomeres (ALT)." (PMID 35953846, 2022).
glioma (continued). "We identified significant associations between age-associated SNVs and mRNA abundance for ATRX and IDH1 in lower grade glioma." (PMID 35017538, 2022). "We treated MOG-G-UVW, U-251, and SF-188 (EV and ATRX KO) high-grade glioma cell lines with different concentrations (5 μM and 10 μM) of BTK, STAT3, and RTK inhibitors for 48 h in order to assess cell viability." (PMID 35406561, 2022). "Additional classification is based on loss of nuclear ATRX chromatin remodeler (ATRX), telomerase reverse transcriptase (TERT) expression and mutations within its promoter, and several DNA methylation subgroups (G-CIMP, Glioma CpG island methylator phenotype)." (PMID 35875157, 2022). "We conclude that ATRX loss-of-function leads to a decrease in CTCF binding and associated heterochromatin, enabling human and murine glioma cells to evade the desirable outcome of therapy-induced senescence." (PMID 34763709, 2021). "Except ATRX, the overexpression of all other genes was found to be significantly correlated with shorter OS of patients with glioma." (PMID 35095717, 2021). "As previously reported, miRNA-1269a facilitates the proliferation and apoptosis of glioma cells by directly targeting ATRX." (PMID 35174066, 2021). "The potential oncogenic role of ATRX in tumorigenesis is reported as a marker for defining the molecular subtype of glioma." (PMID 34944924, 2021). "An alternative decision tree starting with IDH1-R132H staining identified 50/69 IDH1-R132H-positive gliomas that showed ATRX nuclear retention and that required 1p/19q testing to identify 39 oligodendrogliomas." (PMID 34020723, 2021). "With the development of genetics and molecular biology, many molecular biomarkers have been developed for gliomas, such as IDH mutation, ATRX mutation, MGMT methylation status, and 1p/19q status, but they have limitations." (PMID 34136486, 2021). "In this study, we also found that signature 3 was linked to 7+/10−, signature 13 was linked to ATRX mutation and MGMT promoter methylation, and signature 16 was linked to grade in glioma." (PMID 34307451, 2021). "ATRX knockout in murine glioma recapitulates gene expression and open chromatin signatures that are specific to human ATRX-mutant astrocytomas, including drivers of astrocytic lineage and immune-cell chemotaxis." (PMID 34763709, 2021). "To test this, we knocked out ATRX in an immunocompetent intracranial murine model of IDH-mutant glioma." (PMID 34763709, 2021). "We profiled 22 human IDH-mutant grade II/III gliomas via snATAC-seq: 10 ATRX-mutant IDH-A and 12 ATRX wildtype, 1p/19q co-deleted IDH-O tumors." (PMID 34763709, 2021).
glioma (continued). "It is reported that high-grade NF1 glioma exhibited frequent ATRX mutations, while a particular methylation subgroup of sporadic gliomas, the LGm6 subgroup, is enriched with ATRX mutations and assembles epigenetic profiles of NF1 glioma." (PMID 34566848, 2021). "To confirm these results, we used a cell line (named LGG275) that was derived from a diffuse low-grade glioma patient with IDH1 and ATRX mutations." (PMID 33925547, 2021). "Distributed widely in gliomas, ATRX mutations contribute to the development of alternative lengthening of telomeres (ALT), and ATRX loss-of-function mutations have been confirmed to promote ALT." (PMID 34422648, 2021). "Addition of MR diffusion to conventional MRI features provides added diagnostic value in preoperative determination of IDH1, MGMT, and ATRX in patients with glioma." (PMID 34056604, 2021). "In comparison to other studies in which ATRX was found to be mutated only rarely in adult primary GBM, but frequently found in younger adults with lower-grade glioma (WHO grade II/III), we found a high frequency at 30 years that decreases in elderly patients." (PMID 34123356, 2021). "Molecular alterations, such as IDH 1/2 mutations, ATRX mutations, 1p/19q codeletion, TERT promoter mutations, and MGMT promoter methylation have also been highly studied for glioma molecular classification and prognostication." (PMID 34277415, 2021). "ATRX-KO murine gliomas are more heavily infiltrated by immunosuppressive blood-derived monocytic lineage cells than controls, in an IDH-mutant background." (PMID 34763709, 2021). "Genes of these pathways distribute in characteristic patterns in the expression landscape, indicating activation of TEL-related genes in IDH-wt and IDH-O tumors and deactivation of ATRX in IDH-A gliomas." (PMID 34206856, 2021). "DH1, TERT, EGFR, PTEN, ATRX and other key factors are expressed in gliomas as in human GBM, and EGFR is upregulated in tree shrew GBM." (PMID 33768009, 2021). "We found that ATRX knockout in IDH-mutant glioma led to increased infiltration by monocytic-lineage cells expressing Arg1 and Vegfa." (PMID 34763709, 2021). "To model ATRX deficiency in IDH-mutant glioma, we used the immunocompetent glioma model of SB28 cells injected intracranially in C57BL/6j mice as a starting point." (PMID 34763709, 2021). "We found that ATRX-KO glioma cells were more invasive in vitro than ATRX-wildtype controls, in an IDH1R132H background." (PMID 34763709, 2021). "The results showed that except for sex, there were significant differences in age, glioma type, IDH mutation status, ATRX mutation status, 1p/19q status, MGMT promoter methylation status, and survival status between the high- and low-risk groups." (PMID 34136486, 2021). "In infantile and pediatric gliomas, a similar association between the ALT phenotype and ATRX loss has been observed." (PMID 34069193, 2021).
glioma (continued). "By contrast, retained nuclear ATRX positivity in an IDH-mutant glioma should prompt analysis for 1p/19q codeletion in order to distinguish IDH-mutant astrocytoma from IDH-mutant and 1p/19q-codeleted oligodendroglioma." (PMID 33293629, 2021). "1p/19q codeletion status should be determined in all IDH-mutant gliomas with retained nuclear expression of ATRX." (PMID 33293629, 2021). "We find that both human ATRX-mutant gliomas and murine ATRX-knockout gliomas are more heavily infiltrated by immunosuppressive monocytic-lineage cells derived from circulation than ATRX-intact gliomas, in an IDH-mutant background." (PMID 34763709, 2021). "To test if ATRX mediates CTCF binding in IDH-mutant glioma we performed anti-CTCF single-cell Cleavage Under Targets and Tagmentation (scCut&Tag) on ATRX wildtype (scrambled control) and KO SB28+IDH1R132H cells." (PMID 34763709, 2021). "The results showed that there was a positive correlation between NUP37 and most known biomarkers of glioma such as ATRX, EGFR MGMT, CDK4, and so on." (PMID 34264013, 2021). "We introduce molecular (MGMT methylation, IDH mutation, 1p/19q co-deletion, ATRX mutation, and TERT mutations) prediction methods of low-grade gliomas with imaging." (PMID 32111869, 2020). "Patients’ age, KDELC2 expression, IDH1, ATRX, neurofilament, p-AxL, Nur77, H3Lys27, and PDGFRA were associated with glioma patients’ overall prognosis." (PMID 32927743, 2020). "It remains to be seen in future studies how G34 mutations, or coincident loss of ATRX, mitigates the elevation of CGI methylation levels in the telomere-proximal regions, a common feature shared between normal brain tissue and glioma." (PMID 32999376, 2020). "Next, IHC results obtained from the HPA database showed that ATRX had low or moderate staining in glioma tissues but high intensity in normal brain tissues and that it was mainly localized in the nucleus of cells." (PMID 33194637, 2020). "Our study identified that miR-1269a/ATRX is a potential therapeutic target for the treatment of glioma." (PMID 33194637, 2020). "The survival data indicated that glioma patients with a low ATRX level had significantly poorer overall survival than patients with a high level of ATRX expression (P < 0.0001)." (PMID 33194637, 2020).